BDNF (brain derived neurotrophic factor)
Diseases named in the same sentence as BDNF in open-access papers (continued):
Sharing a sentence is not in itself a finding about the gene and the disease.
Anxiety (continued). "Therefore, it would be beneficial for future research to establish a cut-off value for BDNF mRNA expression, similar to what has been done in previous PTSD studies for anxiety indices." (PMID 39595020, 2024). "Mice overexpressing TrkBT1 (i.e. reduced BDNF signaling) showed decreased exploratory activity, whereas mice lacking TrkBT1 (i.e. increased BDNF signaling) showed increased anxiety." (PMID 39619203, 2024). "Our findings are also supported by the fact that mice lacking Trkbt1, with increased mature BDNF signaling, showed increased anxiety." (PMID 39619203, 2024). "Pilocarpine injections significantly suppressed motor activity and exploratory activity and increased anxiety in Sip1wt/fl mice with and without BDNF overexpression." (PMID 39408863, 2024). "Germ-free mice, which are mice grown up without any exposure to micro-organisms, exhibit reduced BDNF levels in the cortex and hippocampus, and showed increased anxiety-like behaviour." (PMID 36834953, 2023). "As far as we know, there were no data combining serum BDNF and anxiety-related variables to explore the correlates of somatic symptoms in patients with panic disorder." (PMID 37533888, 2023). "Here, we found that protein levels of p-ERK, p-CREB and BDNF were significantly increased in claustrum of ACE mice, implying that they are potential downstream signals for claustrum D1RCaMKII in the process of ACE-induced anxiety-like behaviors." (PMID 37351159, 2023). "On the other hand, the performance of the mice implanted with ECB-BDNF devices were not significantly different as compared to the WT unimplanted mice indicating a positive effect of BDNF in reducing anxiety-related behavior." (PMID 37596686, 2023). "Given the presence of anxiety-like deficits in BDNF+/Met mice, social-and non-social stimuli were placed in the corners of two side chambers to minimize the interference of anxiety to social ability." (PMID 37205980, 2023). "From another point of view, decreased BDNF and GAP3 can reduce neuroplasticity in the hippocampus and the PFC, which may be another reason of anxiety‐like behavior observed in treatment groups." (PMID 36942730, 2023). "Physical exercise (PE) may enhance the effect of CBT by improving cognitive function and increasing levels of brain-derived neurotrophic factor (BDNF), a predictor of the effect of CBT in patients with anxiety." (PMID 37468978, 2023). "OCN also increases the secretion of brain-derived neurotrophic factor (BDNF), which subsequently improves the impact on neurodevelopment and function, reduces inflammatory responses, inhibits cell apoptosis, and suppresses anxiety and depressive behaviors." (PMID 38137886, 2023). "Furthermore, we suggest that GHes suppressed anxiety in zebrafish by attenuating the ERK/AP-1/Th1 and BDNF/CREB pathways." (PMID 37663268, 2023). "Prevalence of low-BDNF values in participants with anxiety (P = 0.52) and psychological distress (P = 0.32) was not significantly different from healthy subjects." (PMID 37012351, 2023). "This hypothesis is supported by our previous report that chronic PS resulted in reduced anxiety, decreased plasma CORT, and increased BDNF expression in the hippocampus." (PMID 36498900, 2022). "However, the loss of FTO leads to impairment of neuronal differentiation and a processing defect of brain-derived neurotrophic factor (BDNF) within the hippocampus, which increasing anxiety and impairing the working memory." (PMID 36163017, 2022). "Another finding even reported it is BDNF serum level, not BDNF Val66Met genotype, that was correlated with anxiety personality traits in healthy people." (PMID 35815047, 2022). "None of the anxiety-related indicators correlated with the hippocampal protein levels of BDNF and Syt-1 in the OF and EPM test (P < 0.05)." (PMID 36570704, 2022).
Anxiety (continued). "This study showed that both mouse embryculture with corticosterone (ECC) and maternal preimplantation restraint stress (PIRS) increased anxiety-like behavior (ALB) while decreasing hippocampal expression of glucocorticoid receptor (GR) and brain-derived neurotrophic factor (BDNF) in offspring." (PMID 35433692, 2022). "Increased release of BDNF and enhanced TrkB signaling may be responsible for the induction of PI3K/Akt/mTOR and favorable effects on inflammation, apoptosis, anxiety-related behavior, and cognitive improvement seen in the present study after iTBS." (PMID 35656538, 2022). "Even though the decrease in BDNF among HDP rats was not significant relative to NP rats, there was a significant negative correlation between BDNF levels and anxiety, which was increased in response to HDP." (PMID 35200304, 2022). "In a rat model of PTSD, four weeks of treadmill exercise protocol ameliorated stress-induced enhanced anxiety levels, serum CORT, the BDNF protein level in the hippocampus and serum, and apoptosis markers (Bax, Bcl-2, and Caspase 3) as compared to the sedentary rats." (PMID 36362131, 2022). "Distress reduces the hippocampal BDNF expression, activates the HPA axis and increases anxiety." (PMID 36422338, 2022). "BDNF is a potent neuroprotective agent and post-stroke WBV-induced BDNF increase may be responsible for hippocampal neuronal survival after WBV and improved hippocampal-dependent cognition and anxiety-like behavior observed in the current study." (PMID 36062148, 2022). "In the previous studies, the BDNF promoter activity was decreased in the amygdala after TBI treatment, although it was suggested that decreased amygdaloid BDNF expression is responsible for the elevated anxiety-like response." (PMID 34959450, 2021). "Two tailed Pearson correlation analysis showed that sociability index and time spent in the centre of the open field (anxiety behaviour) had significant negative correlations with plasma BDNF level (r = −0.527, p = 0.009 and r = −0.570, p = 0.001)." (PMID 33503967, 2021). "There does not seem to be a study investigating BDNF and anxiety scores in patients suffering with OA, but there are several studies on BDNF and mood disorders." (PMID 33915758, 2021). "Thus, anxiety and aversive USVs due to ETOH administration are controlled by the BDNF-CRH system and HT7 stimulation regulates this system by increasing the BDNF level in the amygdala." (PMID 33919862, 2021). "We did find RA patients with anxiety had lower serum levels of BDNF compared to those without anxiety symptoms." (PMID 33673283, 2021). "In the PFC and hippocampus of CRS-induced anxiety-model rats, there was an obvious decrease in p-CREB (PFC, p = 0.0081; hippocampus, p = 0.0432) and BDNF (mRNA expression: PFC, p = 0.0003 and hippocampus, p = 0.0234; protein expression: PFC, p = 0.0145 and hippocampus, p = 0.0338)." (PMID 34646421, 2021). "Furthermore, miR-16-5p was predicted to target to BDNF, NPY4R, GLUD1, and FKBP5, which are reported to be involved in the pathophysiology of anxiety and depression." (PMID 33737514, 2021). "Exposure to cyclophosphamide, however, neither prevented reduced brain mass and BDNF expression nor normalized increased tau and anxiety-related behaviors." (PMID 33472690, 2021). "Serum BDNF was significantly lower in male infants than female infants but neither correlated with maternal anxiety symptoms." (PMID 33462179, 2021). "Additionally, BDNF-infused SERT−/− rats presented decreased immobility in the forced swim test and lower anxiety levels in the novelty-induced locomotor activity test compared to controls." (PMID 34068707, 2021). "Furthermore, PGC-1α and BDNF levels have also been altered in rodents with anxiety-like behavior, and both PGC-1α and BDNF can have anxiolytic properties." (PMID 33935687, 2021).
Anxiety (continued). "p-Coumaric acid, a representative active compound from AOM, could activate the BDNF/TrkB/AKT signaling pathway and mediate adult hippocampal neurogenesis, subsequently improving cognitive functions, and reducing anxiety." (PMID 33537297, 2020). "Hence, the anxiety-like effect of HSE seems to be related to a local hippocampal increase in ERK signaling, together with a reduction in CREB and the restoration of BDNF levels." (PMID 33348565, 2020). "Therefore, the ECS influences on the MAPK/ERK signaling pathways, as well as BDNF and p-CREB, are relevant to anxiety-like behaviors and are downstream effector proteins." (PMID 32655658, 2020). "Two important biomarkers, BDNF and IL-1β in serum were assayed to establish a link of the regulatory mechanism of 0.5% GORZ treatment between the central nervous system (CNS) and the circulatory system under alcohol-induced anxiety." (PMID 32606350, 2020). "Additional studies are needed to clarify whether similar changes in BDNF levels in the PFC and anxiety are also seen in female rats exposed to PMS." (PMID 32793001, 2020). "Related studies suggested that early experiences, including the quality and extent of maternal care, exerted long-lasting alterations in social behaviors, anxiety, and fearfulness, along with aberrant HPA axis activity and the expression of brain-derived neurotrophic factor." (PMID 33134294, 2020). "In this study, two types of stress models (EH and PMS) were used to elucidate their effects on the behavior and endocrine function of offspring, as well as the relationship between BDNF expression in PFC and anxiety and spatial memory behavior in adolescent rats that had experienced early stress." (PMID 32793001, 2020). "Exposure to brief separation (EH) did not alter anxiety-like behavior, or BDNF levels, but increased CORT levels compared to CON, but to significantly lower levels compared to PMS." (PMID 32793001, 2020). "In the social defeat stress model, a negative correlation between miR-30a and BDNF was found in the hippocampus of mice, which also exhibited similar impaired social interaction and anxiety-like phenotypes after stress exposure." (PMID 32085670, 2020). "A processing defect of brain-derived neurotrophic factor (BDNF)−a neurotrophic factor involved in the pathophysiology of MDD −was found in the hippocampus of these Fto knockout mice, which presented with deficits in working memory and increased anxiety." (PMID 32984403, 2020). "In an oxidative stress model of anxiety in rats, GSPE (15 g/L/day) treatment over 3 weeks significantly reduced anxiety-like behavior while restoring, among other markers, BDNF levels indicating that oxidative-stress induced changes in behavior can be rescued by grape seed polyphenol treatment." (PMID 31749681, 2019). "The relation between BDNF, the survival of inhibitory interneurons and anxiety is still not established." (PMID 31281833, 2019). "Said differently, the epilepsy condition changes the setpoint (the y intercept of the linear regression function) of the relationship between anxiety and serum BDNF levels, without an apparent change of the slope (the co-variance rule)." (PMID 31331937, 2019). "Gene microarray data in hippocampal tissue revealed that pigs fed lactoferrin had upregulated expression of genes in the brain-derived neurotrophic factor (BDNF) neurotrophic signaling pathway, affecting genes related to organization of the cytoplasm, cytoskeleton, growth of neurites, and anxiety." (PMID 29570610, 2018). "GPS may be useful for developing an agents for the treatment of neuropsychiatric disorders, such as anxiety, due to its antiinflammatory activities and the modulation of NF-κB/iNOS/TLR4/BDNF." (PMID 30460112, 2018). "In contrast, the exposure did not affect general health, body weight, spontaneous activity, motor coordination, anxiety or aggression, and no exposure-related histopathological changes or expression of BDNF were observed." (PMID 29206232, 2017).
Anxiety (continued). "In addition, innate HDAC2 overexpression and decreased H3K9 acetylation in the central nucleus of alcohol-preferring rats correlated with low levels of BDNF, Arc, and NPY and was accompanied with high levels of anxiety-like and alcohol-drinking behaviors." (PMID 27766083, 2016). "It is plausible that innate anxiety is not dependent on BDNF levels because it does not require explicit new learning (unlike fear conditioning)." (PMID 26586578, 2016). "Hence, it is plausible that the combined over‐expression of both hippocampal BDNF and MR mRNA levels in the early‐life corticosterone‐exposed quail might have triggered adaptive coping strategies to prevent potential hippocampal learning impairments or increased anxiety‐like behaviours." (PMID 26999292, 2016). "Innate (i.e. unconditioned) anxiety, as tested on the elevated plus maze, was not affected by reduced BDNF levels in our experiment." (PMID 26586578, 2016). "Though our data on changes in the expression of CRF1R and BDNF in the amygdala upon treatment is preliminary, in view of previous literature on the critical role of CRF1R signaling in anxiety, we believe that the findings are valuable in guiding future studies." (PMID 27042185, 2016). "The absence of significant differences in serum BDNF levels between anxious subjects and healthy donors indicate that BDNF is not a general biomarker of anxiety." (PMID 26539329, 2015). "A recent review of clinical studies showed that BDNF concentrations were lower in individuals with any anxiety disorder compared to those without anxiety but this is not consistent across the literature." (PMID 25734326, 2015). "Concretely, abstinent cocaine users diagnosed with both primary and cocaine-induced disorders (for mood or anxiety disorders) displayed significant decreases in plasma BDNF concentrations (p<0.05) compared to those users with no mood disorders or no anxiety." (PMID 25734326, 2015). "Our results show that BDNF is not a general biomarker of anxiety but serum BDNF levels correlate in a gender-specific manner with ADs subtypes." (PMID 26539329, 2015). "Some of the studies found that anxiety-like behaviors of BDNF(±) mice is indistinguishable from littermate controls, whereas others found that these mice are more aggressive and display increased anxiety." (PMID 24817844, 2014). "Another group found that the same BDNF overexpressing mice showed increased anxiety-like behavior in some but not all tests." (PMID 24817844, 2014). "THA administration failed to affect anxiety behavior of db/db animals, but it significantly revered the reduced levels of BDNF and VEGF/PDGF in the brain." (PMID 23082896, 2012). "In contrast, the well-known induction of brain-derived neurotrophic factor (BDNF) by voluntary exercise was not disrupted by focal irradiation, indicating that hippocampal BDNF levels were not correlated with anxiety under our experimental conditions." (PMID 20862278, 2010). "However, rTg4510 mice spent less time in the center area compared to WT littermates, indicating higher anxiety levels, and BDNF treatment had no significant change in this behavior." (PMID 41480410, 2026). "The impact of blue light on the amygdala exhibits a bidirectional pattern: acute exposure enhances its response to emotional stimuli, whereas prolonged nighttime exposure may reduce brain‐derived neurotrophic factor (BDNF) expression in the amygdala and induce anxiety‐like behaviors." (PMID 40820617, 2025). "The purpose of this study was to ascertain whether or not trazodone hydrochloride affects cognition and anxiety by controlling the BDNF-CREB mechanism." (PMID 41550299, 2025). "In sum, adult female mice can be responsive to P4 for anti-anxiety and anti-depressant behavior, and such effects may be independent of NPRs but require 5α-reduction and actions of BDNF in the hippocampus of E2." (PMID 39940941, 2025).
Anxiety (continued). "While the anxiety index remained unchanged, optogenetic activation of FGFR1 in the dentate gyrus for 12 h per day over 1 week—sufficient to fully activate the FGFR1–Notch–BDNF axis—resulted in a significant increase in sucrose preference and reduction in total immobility time." (PMID 40813470, 2025). "Our findings reveal that patients with clinically relevant anxiety, compared to those without, tended to be younger, had higher BMI, greater arterial stiffness, elevated levels of fibrinogen, and reduced levels of endocan and BDNF." (PMID 40491453, 2025). "The direct effects of neurotrophins on amygdala hyperactivity in MDD are currently under investigation; nevertheless, alterations in BDNF signaling within the amygdala may modify its excitability and lead to heightened negative affect and anxiety symptoms." (PMID 41465304, 2025). "Moreover, the Val66Met rat model, characterized by a valine-to-methionine substitution at position 66 in the rat BDNF gene, exhibited no alterations in anxiety-related behaviors." (PMID 38672038, 2024). "Engaging in PA can also result in the activation of the brain-derived neurotrophic factor (BDNF), which, in addition to its mediation role in the connection between exercise and the growth of new neurons in the hippocampus, regulates stress and anxiety-related behaviors." (PMID 39063430, 2024). "PF can alleviate anxiety and irritable bowel symptoms in rats by inhibiting the leptin/leptin receptor (LepRb) signaling pathway and decreasing phosphatidylinositol-3 kinase (PI3K)/Protein kinase B (AKT) phosphorylation and brain-derived neurotrophic factor (BDNF) expression." (PMID 39220595, 2024). "Therefore, the current study was conducted to determine if plasma BDNF levels differ between depressed patients who respond to antidepressant treatment and those who do not respond, as well as the impact of anxiety in this condition." (PMID 39408702, 2024). "Despite that, serum levels of BDNF were not significantly correlated with anxiety scores in HADS." (PMID 38127937, 2023). "Moreover, the administration of fluoxetine, SSRI, failed to normalize higher anxiety-like behavior in these mice supporting that the actions of SSRI require BDNF." (PMID 36159923, 2022). "Infants who are more fearful or more reactive, showing behavioral inhibition, are reported to be more likely to develop anxiety symptoms later in childhood; thus these results do not support serum BDNF values at birth having predictive value for later development of anxiety." (PMID 35354099, 2022). "We show that chronic immunosuppression with CY prevents hepatosplenomegaly and hypergammaglobulinemia and restores the phenotype of splenic T cells yet does not improve 3xTg-AD performance in anxiety-related tasks or increase brain mass or BDNF or lower phospho-tau levels." (PMID 33472690, 2021). "Thus, manipulations that increased or decreased the BDNF expression level do not always have a clear influence on depressive- or anxiety-like behavior, but these impaired BDNF expressions often lead to an increase in aggressive behavior." (PMID 34769417, 2021). "However, BDNF+/− mice were indistinguishable from wild-type littermates in terms of the levels of locomotor and exploratory activities, anxiety and behavioral despair." (PMID 34769417, 2021). "Therefore, the effect of MAI stimulation at HT7 might be attributed to a change in the pathway that is modulated by the BDNF-CRH system and is related to anxiety-like behaviors and aversive 22-kHz USVs." (PMID 33919862, 2021). "This speculation is in accordance with the findings in animal study, in which stressful environment leads to increased anxiety-related behaviors in BDNF Met/Met mice but not in wild-type mice." (PMID 30524221, 2018).